FPR1 (formyl peptide receptor 1)
Diseases named in the same sentence as FPR1 in open-access papers (continued):
Sharing a sentence is not in itself a finding about the gene and the disease.
sleep disordered breathing (1 paper, 2019). "For the first time, we found defective LXA4 and RvD1 production in association with increased FPR1/FPR2 expression ratio on blood neutrophils in patients with sleep disordered breathing." (PMID 31116781, 2019). "Sleep disordered breathing patients with excessive daytime sleepiness had significantly increased FPR1/FPR2 expression ratio on neutrophil (0.86±0.47, n = 23) as compared with those without excessive daytime sleepiness (0.62±0.28, n = 39, adjusted p = 0.041)." (PMID 31116781, 2019). "Thus, we conducted this prospective cohort study to investigate the relationship between FPR1/2/3/five PFR ligands protein expressions and sleep parameters in 80 patients with sleep disordered breathing and 16 healthy subjects (HS) without snoring history and OSA symptoms." (PMID 31116781, 2019).
small cell lung carcinoma (1 paper, 2023). Small cell lung cancer (SCLC) is a highly aggressive malignant neoplasm, accounting for 10-15% of lung cancer cases, characterized byrapid growth, and early metastasis. "Lately, it was described that FPR1 mRNA levels in total plasma can prognoses small cell lung cancer (SCLC) and NSCLC." (PMID 37813634, 2023).
systemic sclerosis (1 paper, 2025). A chronic disorder, possibly autoimmune, marked by excessive production of collagen which results in hardening and thickening of body tissues. "In systemic sclerosis, it has been reported that mitochondria-derived N-formylmethionine induces excessive neutrophil activation and generation of neutrophil extracellular traps through an FPR1-dependent mechanism." (PMID 39849390, 2025).
vasculitis (1 paper, 2022). "Neutrophil activating factors such as fMET peptides are markedly increased in plasma from vasculitis and enhance inflammation through FPR1-mediated neutrophil activation." (PMID 35768848, 2022). "Thus, our findings suggest that plasma from patients with vasculitis induces ROS through an FPR1- and NADPH oxidase-dependent manner." (PMID 35768848, 2022). "Finally, we investigated whether fMET/FPR1-mediated signaling can drive neutrophil activation in patients with vasculitis." (PMID 35768848, 2022).
tumor (125 papers, 1999 to 2026). "They demonstrated that formyl peptide receptor 1, which recognizes annexin-1 in dying tumor cells, was affected only by single nucleotide polymorphisms in the formyl peptide receptor 1 (Fpr1) gene." (PMID 35806328, 2022). "AnxA1 then binds to FPR1 on dendritic cells, which phagocytose and kill malignant cells, but also present tumour-associated antigens, which are then recognized and eliminated by cytotoxic T lymphocytes." (PMID 33810523, 2021). "For example, cell surface Anxa1 stimulates formyl-peptide receptor 1 (FPR1), which is implicated in anti-tumor immune responses elicited by anthracyclines or oxaliplatin." (PMID 33446132, 2021). "In the present study, we found that the expression of FPR1 was associated with tumor serosal invasion." (PMID 28724995, 2017). "The results showed that FPR1 mRNA expression level was associated with tumor size (p < 0.05) and serosal infiltration (p < 0.001)." (PMID 28724995, 2017). "Our results are supported by microarray survival data from human tumor samples, demonstrating that a high FPR1 expression is associated with significantly lowered overall patient survival." (PMID 27432059, 2016). "Radioligands targeting FPR1 could provide a unique opportunity to better track FPR1 expression and tumor associated FPR1 activity in vitro and in vivo." (PMID 40940450, 2025). "Furthermore, FPR1 overexpression has been registered in gastric cancer in association with tumor progression and an unfavorable prognosis." (PMID 41283264, 2025). "FPR1 mRNA expression was also associated with tumor serosal infiltration in CRC patients." (PMID 32284754, 2020). "However, Fpr1 genotypes of c.289C>A, c.306T>C, c.546C>A, c.576T>C>G, and c.1037C>A showed significant associations with the tumor size in CRC patients, indicating their potential role in the progression of CRC." (PMID 32284754, 2020). "FPR1 mRNA expression was also associated with tumor serosal infiltration." (PMID 28724995, 2017). "Importantly, the ANXA1:FPR1 interaction has been implicated in the tumor microenvironment of several malignancies, indicating that the E. faecalis-infected wound niche mimics the anti-inflammatory transcriptional program of the tumor microenvironment." (PMID 38767331, 2024). "Additionally, CTHRC1 overexpression induced tumor associated macrophage infiltration via AnxA1/FPR1 and GRN/TNFRSF1A signaling pathway, indicating CTHRC1 might be a promising predictive factor for immunotherapy." (PMID 37404760, 2023). "Furthermore, FPR1 mRNA expression was associated with the size of tumor and serosal infiltration." (PMID 28724995, 2017). "The first report suggests a positive correlation between FPR1 and GC progression, while the second a tumor suppressor role of the receptor in GC." (PMID 41425092, 2025). "The mechanism study shows that tumor cell directly triggers apoptosis of DCs through molecular pair ANXA1:FPR1/3." (PMID 40484878, 2025). "Specifically, the interaction between ANXA1 and FPR1 in DCs enhances anti-tumor immunity by promoting the phagocytic uptake of dead cell antigens by DCs." (PMID 41035636, 2025). "Obviously, targeting FPR1 with agonists that induce its pro-resolving, anti-angiogenic and tumor suppressive activities is another possible strategy." (PMID 41425092, 2025). "ANXA1 facilitates dendritic cell (DC) interactions with tumor debris by binding to formyl peptide receptor 1 (FPR1), while HMGB1 drives DC maturation by interacting with TLR4." (PMID 40004078, 2025). "Among these clusters, C0 presents the highest level of FPR1/3, which partially addresses the decrease of the population during tumor evolution." (PMID 40484878, 2025). "The endogenous ligand ANXA1, abundant in deceased tumor cells, enhances immune response and the migration of glioblastoma cells through the FPR1 pathway." (PMID 39445161, 2024). "Formyl peptide receptor 1 (FPR1) is involved in a wide range of physiopathological processes in various tumor cells." (PMID 37747648, 2023).
tumor (continued). "It has been reported that FPR1 can exert a tumor suppressor function in human GC by inhibiting angiogenesis and that silencing of the receptor increases the constitutive proangiogenic potential of GC cells." (PMID 37839346, 2023). "In this study, the overexpression of SIRT3 significantly decreased the expression of FPR1 in tumor cells under a hypoxic environment." (PMID 37747648, 2023). "We found that the secretion of SAAs by damaged hepatocytes facilitated tumor invasion by recruiting FPR1+ macrophages and subsequent M2 polarization." (PMID 37337030, 2023). "FPR1 is involved in a wide range of physiopathological processes, such as cell migration, invasion, and tumorigenicity, in various tumor cells, and was found to promote cardiovascular disease progression." (PMID 37747648, 2023). "Here, we aimed to describe the interaction between the AnxA1/FPR1 and the Interleukin-6 (IL-6) signaling pathways and their role in the tumor microenvironment (TME)." (PMID 35626741, 2022). "In particular, its pro-tumor mechanism of action can be due to the ability to bind the formyl peptide receptors (FPRs), in particular the isoforms FPR1 and FPR2." (PMID 36230687, 2022). "Ac2-26 has been shown to regulate leukocytes and other tumor cell migratory events through interactions with formyl peptide receptors (FPRs), and thus we examined the expression of FPR1, FPR2, and FPR3 in BC cells by RT-qPCR." (PMID 36414640, 2022). "FPR1 has been found to be overexpressed on some tumor cells and mediating antitumor immunity and metastasis." (PMID 35493068, 2022). "Single cell tracking profiles extrapolated by OOC system displayed that FPR1 expressed by immune cells, particularly dendritic cells (DCs), is required to “sense” Anxa1 emanated from dying tumor cells and to migrate toward them engaging in stable interactions." (PMID 33842539, 2021). "Urokinase plasminogen activator receptor (uPAR) interacts with formyl peptide receptor 1 (FPR1) and promotes tumor cell adhesion to mesothelial cells of peritoneum and vitronectin." (PMID 33859913, 2021). "For example, FPR1 has a dual role in cancer development, playing a promoting role in glioblastoma and, conversely, tumor-suppressing functions in gastrointestinal cancers." (PMID 34220836, 2021). "The interaction of ANXA1 with the formyl peptide receptor 1 (FPR1) in immature DCs promote the uptake of tumor antigens." (PMID 34198850, 2021). "FPR1 and FPR3 are macrophage gene markers, participating in neutrophil recruitment 71 and tumor-associated inflammation." (PMID 34326696, 2021). "Annexin-1 has been suggested to enhance the interaction between dying cancer cells and tumor-infiltrating DCs expressing formyl peptide receptor 1 (FPR1)." (PMID 33406603, 2021). "Subsequently, neutrophils infiltrated the core area of tumor tissues through formylpeptide receptor 1 (FPR1) secreted by GBM cells to promote tumor growth, invasion and angiogenesis." (PMID 34211978, 2021). "The small molecule FPR1 is expressed in different types of tumours and plays an important role in tumour expansion resistance and recurrence." (PMID 34857818, 2021). "It has been studied that inhibiting FPR1 activity in NB cells decreases tumor growth in xenograft models; however, overexpression increases tumor burden." (PMID 35250903, 2021). "Human breast cancer cells also express aberrant FPR1 and 2, which are activated by Anx A1 to increase tumor cell growth." (PMID 32038501, 2020). "Our previous study found that the expression of FPR1 was related to tumor serosal invasion in CRC patients." (PMID 32284754, 2020). "In our previous study, the expression of FPR1 has been identified to be related to tumor serosal invasion in CRC patients." (PMID 32284754, 2020). "Although the expression of FPR1 in healthy, non-immune human cells is low13–15, it has been shown that a number of tumours express significant levels of FPR1." (PMID 33057069, 2020).
tumor (continued). "Again, we observed a higher level of FPR1 expression in the periphery of the hypoxic/necrotic core of the xenoplanted tumour." (PMID 33057069, 2020). "This clearly demonstrates the usefulness of FPR1 antagonists, particularly in treatment aggressive tumours." (PMID 33057069, 2020). "Our observation that FPR1 expression is particularly elevated in the periphery of the necrotic/hypoxic core, both in a 3D spheroid model and in xenografted tissue, strengthens the correlation of FPR1 axis to tumour necrosis." (PMID 33057069, 2020). "IHC highlighted variable expression of FPR1 both in the cytoplasm and on the plasma membrane of tumor cells." (PMID 31703596, 2019). "Conversely, the remaining 70.3% (n = 26) of cases exhibited moderate or intense FPR1 expression in at least 80% of tumor cells." (PMID 31703596, 2019). "A diffuse staining of the epithelial tumor cells using anti-FPR1 Ab was obtained in all sections, with a prominent staining of plasma cell membranes, often observed in positive tumor cells." (PMID 31703596, 2019). "The participation of FPR1 on angiogenesis has been preferentially shown in cancer conditions, and depends on a complex scenario in the tumor microenvironment." (PMID 30250432, 2018). "In fact, uPAR over-expression in tumor cells, controls cell migration and invasion by the recruitment of integrins and FPR1 on cell surface and regulating their signaling pathways." (PMID 29670612, 2018). "Release of Annexin A1 has also been described after anthracyclines treatment, stimulating the Formyl Peptide Receptor 1 (FPR1), thus directing the final trajectory of DCs to dying tumor cells." (PMID 30459758, 2018). "High expression of FPRs has also been detected in several cancers but the functions of FPR1 in tumor invasion and metastasis is poorly understood." (PMID 28724995, 2017). "Since the expression of FPR1 was significantly increased in CRC tissues compared with adjacent non-tumor tissues, we further determined the cellular source of FPR1 in these tissues using immunofluorecence staining." (PMID 28724995, 2017). "We found that FPR1 was localized to the cytoplasm and plasma membrane of both primary colorectal epitheliums and tumor infiltrating myeloid cells, as well as in the two colorectal cell lines." (PMID 28724995, 2017). "FPR1 protein expression was both in the colorectal epitheliums and tumor infiltrating neutrophils/macrophages." (PMID 28724995, 2017). "Since both uPAR and FPR1 are involved in tumor progression, the uPAR-FPR1 interaction is an attractive therapeutic target." (PMID 28465589, 2017). "For SK-N-AS FPR1 knockdown cells, the median time to a tumor volume of 0.2 cm3 was more than 50 % longer compared to CTR (55 vs. 36 days)." (PMID 27432059, 2016). "FPR1 as the other two FPRs play a pivotal role in inflammatory response, tissue repair, tumor growth, physiological and pathological angiogenesis." (PMID 27259239, 2016). "To assess the role of FPR1 in tumor formation in vivo, we developed a set of SK-N-AS cell clones with either an overexpression or shRNA-mediated knock-down of FPR1." (PMID 27432059, 2016). "Three groups of nude mice, with 10 animals in each group, were injected with control shRNA, FPR1 shRNA and FPR1 cDNA expressing cells in the hind flanks, and tumor formation was monitored." (PMID 27432059, 2016). "Accumulating evidence demonstrates that FPR1 is also involved in the tumor progression of solid tumors." (PMID 27323409, 2016). "Our results are in line with previous findings, which showed a role for FPR1 in malignant tumor cell activity." (PMID 25894595, 2015). "Immunohistochemical analysis of GBM samples (FFPE) showed that FPR1 has a relative diffuse cytoplasmic staining in tumor cells." (PMID 25894595, 2015). "Another classical chemoattractant GPCR, the FPR1 variant FPR2, has also been reported to participate in recruiting MSCs into tumor tissues to promote the formation of neovasculature in response to tumor-derived ligand LL-37." (PMID 25110692, 2014).
tumor (continued). "Interestingly, not only FPR1 participates and is necessary for maintaining homeostasis, but it also exerts strong tumor suppressor properties in this tissue." (PMID 41425092, 2025). "Recently, FPR1 was shown to be expressed in different types of tumor cells and could play a significant role in tumor growth and invasiveness." (PMID 37839346, 2023). "ATP and ANXA1 ligate purinergic receptors of the purinergic receptor P2X 7 (P2RX7) type and formyl peptide receptor 1 (FPR1), respectively, thus facilitating the chemoattraction and homing of migratory cDC1s into the tumor bed, into the proximity of stressed and dying cancer cells." (PMID 37907944, 2023). "Furthermore, both CD163 and FPR1 played a vital and positive role in the tumor-promoting signal pathways in order to promote the development of HGSOC." (PMID 38115318, 2023). "On the other hand, it has been proposed that FPR1 may act as a tumor suppressor by inhibiting angiogenesis in GC xenografts because silencing of FPR1 augmented vessel density in tumor stroma." (PMID 37839346, 2023). "We found CAFs which highly expressed CTHRC1 (from F04 and F08) and tumor associated macrophages were mediated by a different set of ligand-receptor pairs, including THY1/aXb2 complex, GRN/TNFRSF1A, CD99/PILRA, CD74/MIF, APP/CD74, ANXA1/FPR1, etc." (PMID 35928443, 2022). "As the progression of metastasis requires collusion between cancer cells and localized accumulations of myeloid cells, the findings in this study advocate that ANXA1 in the tumor microenvironment is partially responsible for recruitment of infiltrating microglia through activation of FPR1 and FPR2." (PMID 35382852, 2022). "The administration of cyclosporine H, an FPR1 antagonist, abolishes the antitumor effect of chemotherapy, suggesting that FPR1 expression in the host and annexin A1 expression in tumor cells are required for the chemotherapeutic inhibition of tumor growth." (PMID 34638242, 2021). "Moreover, FPR1 has been demonstrated to regulate the proliferation, invasion, and angiogenesis of tumor cells." (PMID 33345275, 2021). "Interestingly, FPR1 silencing significantly enhances GC tumorigenicity, suggesting that this receptor exerts a tumor suppressor function by inhibiting angiogenesis." (PMID 33804219, 2021). "Interestingly, in the OOC setting only DC with an intact FPR1 successfully migrate toward anthracycline-killed tumor cells and capture apoptotic bodies released from these dying cells." (PMID 33842539, 2021). "One of the first studies aimed to assess the effects of pharmacological treatments for cancer therapy by using an on chip approach is represented by a study addressing the role of formyl peptide receptor 1 (FPR1)/annexin a1 (Anxa1) axis in anti-tumor response to anthracycline-based chemotherapy." (PMID 33842539, 2021). "Moreover, the S90P and S90E substitutions in the uPAR protein can cause upregulation and downregulation of cell migration, respectively, by mediating agonist-triggered activation and internalization of FPR1 117, thus inhibiting tumor metastasis." (PMID 34729105, 2021). "In addition, ANXA1 appears to have a distinct tumour promoting effect by binding and activating FPR1, the expression of which is shown to be elevated in many tumours." (PMID 33057069, 2020). "Moreover, GBM cells with necrosis release an FPR1 agonist Anx A1that actives the receptor on tumor cells to exacerbate the invasive behavior." (PMID 32038501, 2020). "However, another study showed that AnxA1 initiated autocrine signaling in breast cancer via FPR1 and led to an increase in tumor growth and metastasis." (PMID 31336833, 2019). "Conversely, FPR1 has demonstrated tumor suppressor functions in gastric cancer." (PMID 31336833, 2019). "FPR1 are expressed both in the colorectal epitheliums and tumor-infiltrating myeloid cells." (PMID 28724995, 2017).